CAV3 (caveolin 3)
Diseases named in the same sentence as CAV3 in open-access papers (continued):
Sharing a sentence is not in itself a finding about the gene and the disease.
Sepsis (2 papers, 2021 to 2025). Sepsis is defined as life-threatening organ dysfunction caused by a dysregulated host response to infection. "These contrasting findings suggest that cardiac response to sepsis may vary depending on the type of septic stimulation, and the precise mechanisms underlying Cav-3’s role in sepsis require further exploration." (PMID 40041164, 2025). "The cause of CAV3 overexpression in sepsis is still unknown." (PMID 33927797, 2021). "Our results indicate that sepsis leads to increased expression of CAV3 in the heart, and the treatment with verapamil can directly or indirectly modulate its expression resulting in a reduction of mortality rates and cardiac injuries." (PMID 33927797, 2021). "The results showed a significant increase in the levels of CAV3 expression only 24 hours after the severe sepsis induction (SSI) when compared to the values observed in the hearts of the control group (sham)." (PMID 33927797, 2021). "Our study demonstrates that cardiac changes induced by sepsis provide a different response regarding the expression of CAV3, as septic animals showed a significant increase in CAV3 levels." (PMID 33927797, 2021). "Our results indicate that CAV3 has a vital role in cardiac dysfunction development in sepsis and that the regulation of L-type calcium channels may be related to its expression." (PMID 33927797, 2021). "The purpose of the present study was to test the hypotheses that sepsis induces CAV3 overexpression in the heart, and the regulation of L-type calcium channels directly relates to the regulation of CAV3 expression." (PMID 33927797, 2021). "Additionally, reduced expression of CAV3 led to a reduction of sepsis-induced cardiac injuries and a decreased mortality rate." (PMID 33927797, 2021). "Severe sepsis increases the expression of CAV3 in the heart, as immunostaining in our study showed CAV3 presence in the cardiomyocyte membrane and cytoplasm, in comparison with our control groups (without sepsis) that showed CAV3 presence predominantly in the plasma membrane." (PMID 33927797, 2021).
anaphylaxis (1 paper, 2019). An acute hypersensitivity reaction that occurs from exposure to an allergen. "This approach identified several genes that are associated with aging (ATP2B2, CAV3, CNTN3, CTNNA2, GRID2), inflammation (ATP2B2, CAV3, RAD18, KBTBD8), vascular permeability (SFXN5, RAD18) and anaphylaxis (CAV3, RAD18, CTNNA2, ATP2B2 and GRID2)." (PMID 31701027, 2019).
autism spectrum disorder (1 paper, 2025). A spectrum of developmental disorders that includes autism, and Asperger syndrome. "Additionally, mutations of all CaV3 channels have been linked to autism spectrum disorder." (PMID 41465576, 2025).
Autosomal dominant limb-girdle muscular dystrophy type 1C (1 paper, 2025). Autosomal dominant limb-girdle muscular dystrophy type 1C (LGMD1C) is a limb girdle muscular dystrophy (LGMD; see this term) caveolinopathy characterized by weakness in limb-girdle muscles, calf muscle hypertrophy and lack of respiratory and cardiac involvement. "Mutations in the CAV3 gene have been linked to several muscle disorders, including autosomal dominant limb-girdle muscular dystrophy type 1C (LGMD-1C), characterized by progressive weakness of the pelvic and shoulder girdle muscles." (PMID 40243482, 2025).
Brody disease (1 paper, 2021). "Other genes examined in these NDM patients were CAV3, ATP2A1 (Brody disease) and HINT1 (hereditary neuromyotonia with axonal neuropathy)." (PMID 33263785, 2021).
cardiotoxicity (1 paper, 2017). Toxicity that impairs or damages the heart. "Our results imply that up-regulation of Cav-3, activated integrins, and MG53 in our Dau-induced cardiotoxicity model may reflect the critical need for membrane repair processes when anthracycline-induced membrane injury occurs." (PMID 28498861, 2017).
channelopathies (1 paper, 2020). "Alternative splicing could contribute to the clinical severity of Cav3 channelopathies, as documented by in vitro studies showing that disease-associated mutations exhibit distinct electrophysiological properties when reproduced in different splice variants." (PMID 32638069, 2020).
ductal carcinomas in situ (1 paper, 2023). "The change in CaV3 protein expression and subcellular localization are consistent with the neoplastic transformation stages of mammary epithelial cells, evident in early neoplastic lesions, such as ductal carcinomas in situ." (PMID 36790286, 2023).
dysferlinopathy (1 paper, 2023). "In aged dysferlin null mice and individuals with dysferlinopathy, lack of dysferlin alters expression of many dysferlin-associated proteins including AHNAK, Annexin A2, Calpain-3, Caveolin-3 and MG53." (PMID 36653852, 2023).
episodic ataxia type 1 (1 paper, 2025). A frequent form of hereditary episodic ataxia characterized by brief episodes of ataxia, neuromyotonia, and continuous interictal myokymia. "Genetic conditions associated with muscle twitching include rippling muscle syndrome caused by caveolin-3 (CAV3) mutations and episodic ataxia type 1 linked to mutations in the potassium channel gene KCNA1." (PMID 40718168, 2025).
experimental autoimmune encephalomyelitis (1 paper, 2023). An autoimmune demyelinating disease of the central nervous system that is produced experimentally in animals by the injection of homogenized brain or spinal cord in Freund's adjuvant. "A short synthetic peptide from the C-terminal part of the caveolin-3 structure was tested for experimental autoimmune encephalomyelitis (EAE) treatment in rats." (PMID 37893228, 2023).
familial cardiomyopathy (1 paper, 2025). An instance of cardiomyopathy that is caused by an inherited modification of the individual's genome. "As expected, SVIL knockdown markedly decreased the levels of caveolin-3 and α-sarcoglycan which were previously identified in familial cardiomyopathy." (PMID 41144497, 2025).
invasive ductal carcinoma (1 paper, 2023). "In conclusion, our results suggested that as the mammary epithelium advanced in the neoplastic transformation model for invasive ductal carcinoma a decrease in nuclear expression of CaV3 channels was observed." (PMID 36790286, 2023).
large cell lung carcinoma (1 paper, 2023). "Talbot Lung Statistics and Okayama Lung Statistics showed that CAV3 was downregulated in squamous cell lung carcinoma and large cell lung carcinoma." (PMID 37497407, 2023).
Left ventricular dilatation (1 paper, 2018). Enlargement of the chamber of the left heart ventricle. "The left ventricular dilatation and reduced fractional shortening and ejection fraction observed in vivo in Cav-3 KO mice confirm previous work using a different Cav-3 KO mouse line." (PMID 30028203, 2018).
paroxysmal AF (1 paper, 2017). "Participants with lower serum Cav-3 concentrations were more likely to become paroxysmal AF (P < 0.05)." (PMID 28420984, 2017). "In further tertile studies, subjects in the lower tertile of Cav-3 concentrations were more likely to become paroxysmal AF and had much lower LAD (P < 0.05)." (PMID 28420984, 2017). "Accordingly, we could speculate that Cav-3 has a certain relationship with the paroxysmal AF, LAD, and incident HF." (PMID 28420984, 2017).
schizophrenia (1 paper, 2025). A major psychotic disorder characterized by abnormalities in the perception or expression of reality. "Dysregulated Cav3 channel activity is also associated with spindle and slow-wave impairments in schizophrenia, with a localized reduction in Cav3.3 activity in TRN as one potential cause of observed spindle abnormalities." (PMID 40995120, 2025).
myopathies (14 papers, 2010 to 2024). "For muscle cells, new aspects become relevant after a recent report about caveolin 3 (Cav3) mutations, which cause various forms of myopathies." (PMID 32164381, 2020). "Mutations in the CAV3 gene cause different types of myopathies with altered membrane integrity and repair, expression of muscle proteins, and regulation of signaling pathways." (PMID 31036801, 2019). "This minor indication for muscular defects in syndapin III KO mice and the fact that also some of the human CAV3-associated myopathies show relatively mild symptoms and late onset, respectively, prompted us to next subject aged mice to physical exercises." (PMID 29202928, 2017). "This pathophysiology in syndapin III KO muscles is reminiscent of human myopathies associated with CAV3 mutation." (PMID 29202928, 2017). "The skeletal muscle phenotype of this transgenic mouse showed severe myopathy, with loss of caveolin-3, resulting in muscle fiber degeneration, motor deficits and disability." (PMID 23717655, 2013). "Different phenotypes may be linked to the same mutation, but the co-existence of myopathy and cardiac disease has been rarely described, suggesting that the molecular networks supporting the role of cav-3 in skeletal muscle and heart may differ." (PMID 38256054, 2024). "Our results uncover new pathophysiological mechanisms that may prove relevant to myopathies caused by Cav3 or Bin1 dysfunction." (PMID 37083699, 2023). "In our microarray assays, CCNA1 expression was detectable at very low levels in healthy controls as well as in some other myopathies such as CAV3, DYSF and FHL1." (PMID 24019929, 2013). "For patients with myopathy with muscle weakness and atrophy, CAV3 gene transfection may help to improve muscle metabolism and increase the number of muscle cells, thereby restoring the morphology and function of muscle fibers." (PMID 29206848, 2017). "The PTRF gene should be investigated in patients with hyperCKemia, mild myopathy associated with spontaneous or percussion-induced muscle contractions like rippling or mounding, and no CAV3 mutation." (PMID 24024685, 2013). "Tamoxifen might also prove useful in other myopathies where t-tubule defects secondary to increased DNM2 levels contribute to the pathogenesis, such as BIN1-related CNM and caveolin-3 and dysferlin-related myopathies." (PMID 30451843, 2018).
cancer (12 papers, 2012 to 2023). A tumor composed of atypical neoplastic, often pleomorphic cells that invade other tissues. "Both CaV1 and CaV3 channels have been implicated in the proliferative pathophysiology of various cancers, and their contributions are reviewed below." (PMID 26010603, 2015). "However, CaV3 knockdown was associated with drug-resistant cancer therapy." (PMID 36790286, 2023). "We further explored the expression levels of CAVs in another independent data set (TIMER database) and validated that CAV1, CAV2, and CAV3 were expressed low in most cancer, especially in BC." (PMID 36147736, 2022). "As a sub-structure of caveolae, CAV3 only revealed association with CAVIN4, which were both little expressed in cancer cells." (PMID 34513683, 2021). "Other CCBs are well tolerated such as the diuretic amiloride, which also targets CaV3, and it may be beneficial in the treatment of cancers where CaV3 is functionally overexpressed." (PMID 27342111, 2016). "The Cav3 inhibitors including mibefradil are able to inhibit cancer cell proliferation." (PMID 26010603, 2015). "From the differential genes involved in these pathways, we identified several gene clusters uniquely upregulated in the CAFWPOI 4-5 type; neuronal development and function-related (RELN, MYH10, CACNB4, OXTR, CAV3, CHRM2) and inflammation and cancer-related (RELN, IL21R, EDNRB, CAV3, OXTR)." (PMID 36045118, 2022).
heart disease (7 papers, 2012 to 2024). "The pathological mechanisms of hereditary cardiac diseases due to CAV3 mutations that have been described so far reported a direct influence of the CAV3 mutants on the activity of membrane ion channels localized within caveolae (Nav 1.5, Cav1.2, Kir2.1, Kv4.2, HCN4)." (PMID 38256054, 2024). "Considering that abnormal loss of myocytes can play a mechanistic role in lethal cardiac diseases, we suggest that the detrimental effect of Cav-3 V82I variant on cell viability may participate in determining the susceptibility to cardiac death." (PMID 24917393, 2014). "The protein product of PDLIM3 is predicted to interact with the protein products of several other genes that are linked with heart disease, including MYBPC3, ACTN2, and CAV3." (PMID 32013268, 2020). "Several susceptibility genes have been identified for the congenital forms of these cardiac diseases, including caveolin-3 (Cav-3) gene." (PMID 24917393, 2014). "Given the critical role of caveolins in cell physiology and the localization of Cav-3 in cardiac muscle, it is of little surprise that Cav-3 is a player in both cardiac disease and protection." (PMID 22934034, 2012). "Interestingly, mice null for caveolin-3 and caveolin-1 develop severe heart disease, while caveolin-3 over expression induces a Duchenne-like phenotype in mice." (PMID 25914646, 2015). "In particular, caveolin-1 (Cav-1) and caveolin-3 (Cav-3) have been identified as potential regulators of vascular dysfunction and heart disease and might even confer cardiac protection in certain settings." (PMID 22934034, 2012). "There has lacked clinical data to confirm the effect of Cav-3 on heart disease, even less on AF." (PMID 28420984, 2017).
tumor (7 papers, 2015 to 2024). "For this purpose, IHC analysis carried out on serial tumor sections showed that MURC/cavin-4 staining consistently overlaps that of Cav-3 in a significant number of foci/cells." (PMID 26086601, 2015). "This analysis highlighted a diffuse expression of Caveolin-3 and α-smooth muscle actin (α-SMA), both sensitive markers of eRMS, further confirming the generation of eRMS tumor in our mouse model." (PMID 33671425, 2021). "In our in vivo system, major changes in skeletal muscle architecture became noticeable between three and seven weeks after Ad-Cre infection when a tumor mass expressing eRMS markers, such as α-SMA and Caveolin-3, was observed." (PMID 33671425, 2021). "In 2005, a study reported Cav-3 to be expressed in the more differentiated eRMS and aRMS subsets, thereby configuring this protein as a useful marker to assess the degree of differentiation or detect residual tumor cells that may undergo differentiation following chemotherapy." (PMID 26086601, 2015). "We found MURC/cavin-4 to be expressed, often concurrently with Cav-3, in mouse and human RMS, as demonstrated through in silico analysis of gene datasets and immunohistochemical analysis of tumor samples." (PMID 26086601, 2015). "Also, all nine included significant studies which presented that CAV3 was expressed low in tumor tissues when compared to non-tumor tissues." (PMID 36147736, 2022).
cardiovascular diseases (5 papers, 2012 to 2024). "The major pathological cardiovascular features associated with change in Cav-3 function are those leading to hypertrophy and myopathy, which are hallmarks of cardiovascular disease." (PMID 22934034, 2012). "Variants of caveolin 3 (CAV3) play important roles in cardiovascular diseases." (PMID 38671439, 2024). "Previous research has provided evidence highlighting the participation of CAV3 in the development of diverse cardiovascular diseases, including cardiac hypertrophy, contractile dysfunction, myocardial ischaemia and heart failure." (PMID 38671439, 2024). "Caveolin-3 is a muscle-specific protein on the membrane of myocytes correlated with a variety of cardiovascular diseases." (PMID 35329921, 2022).
neurological disorders (3 papers, 2019 to 2023). "CAv3 has been shown to be a mediator of subthreshold oscillations and excessive rhythmicity in neurologic disorders such as tremor, neuropathic pain, epilepsy, and Parkinson's disease." (PMID 31244760, 2019). "Under abnormal states, the TTCC CAv3 subtype is upregulated or has increased activity that makes it a prime target for neurologic disorders such as ET." (PMID 31244760, 2019).
skeletal muscle disorder (3 papers, 2014 to 2024). A disease involving the skeletal muscle tissue. "We decided to focus on three specific cav-3 mutations (Δ62-64YTT; T78K and W101C) found in heterozygosis in patients suffering from skeletal muscle disorders." (PMID 38256054, 2024).
genetic disorders (2 papers, 2019 to 2024). "In this study, we explored the mechanical role of caveolae in human muscle cells and their possible deregulation in caveolinopathies, a family of muscle genetic disorders involving mutations in the CAV3 gene." (PMID 31036801, 2019).
muscular disorders (2 papers, 2013 to 2018). "Cav1 is involved in cholesterol transport and signal transduction, whereas caveoline-3 (Cav3) is specific to skeletal, smooth, and cardiac muscle and results in muscular disorders when defective." (PMID 29457121, 2018). "Importantly, cyclin A1 RNA levels of FSHD were not only higher compared to healthy controls but also to patients with the other muscular disorders: CAV3, DYSF, and FHL1." (PMID 24019929, 2013).
CAV3 also shares sentences with these, for which no sentence is quoted: hypertrophy (4 papers); cardiac arrhythmia (3); familial hypertrophic cardiomyopathy (3); neuromuscular disease (3); Type 1 Diabetes (3); acute myocardial infarction (2); infection (2); Ventricular hypertrophy (2); Alzheimer disease (1); angina pectoris (1); atrial flutter (1); autoimmune (1); cardiac arrest (1); centronuclear myopathy (1); congenital cardiomyopathies (1); congestive heart failure (1); coronary artery disease (1); dermatomyositis (1); diarrhoea (1); Emery-Dreifuss muscular dystrophy (1); Encephalopathy (1); essential tremor (1); facioscapulohumeral muscular dystrophies (1); gallstones (1); hypoplastic left heart syndrome (1); inherited rippling muscle disease (1); juvenile dermatomyositis (1); migraine (1); muscular atrophy (1); Myalgia (1).
A further 16 diseases each share a sentence with CAV3 in 1 paper.